HIF1A (hypoxia inducible factor 1 subunit alpha)
Diseases named in the same sentence as HIF1A in open-access papers (continued):
Sharing a sentence is not in itself a finding about the gene and the disease.
asthma (54 papers, 2011 to 2026). "Zisuzi Decoction ameliorates AHR and partially reverses airway remodeling through inhibition of PI3K/AKT1/mTOR, JAK2/STAT3, and HIF‐1α/NF‐κB signaling pathways, demonstrating effectiveness in cough‐variant asthma management." (PMID 41426510, 2025). "Herein, we aimed to determine the effect of vitamin D (Vit D) and underlying mechanisms on asthma‐induced lung injury via regulation of HIF‐1α/Notch1 (hypoxia‐inducible factor 1 alpha/neurogenic locus notch homolog protein 1) signaling during autophagy." (PMID 35959262, 2022). "Prominent among these mechanisms are the fact that asthma causes aberrations of synaptic tissues and blood vessels, elevated levels of hypoxia-inducible factor-1alpha (HIF-1α) and hypoxia-induced factor-2α (HIF-2α)." (PMID 36203679, 2022). "HIF-1α can also cause asthma by means of airway smooth muscle remodeling, which is in line with our findings." (PMID 33980319, 2021). "In summary, we found that asthma caused the impairment of learning and memory, aberrations of synaptic tissues and blood vessels, increased levels of HIF-1α and HIF-2α." (PMID 34248632, 2021). "Some studies have shown that the hypoxia inducer HIF-1α is associated with oxidative stress and may affect asthma pathogenesis." (PMID 34760922, 2021). "Under the circumstances of asthma, hypoxia may be one of the main causes of elevated apoptosis in testis, as evidenced by the induction of HIF-1α expression." (PMID 26938720, 2016). "This suggests that the effect of dexamethasone on asthma management is related to its inhibition of Hif-1α-glycolysis-lactate axis and resultant lactylation modification." (PMID 41531823, 2026). "Transcriptomics and cross-species analysis integrated rat signatures with human asthma datasets using KEGG enrichment to identify conserved HIF-1α-related pathways." (PMID 41878326, 2026). "They find that dexamethasone downregulates OVA-induced Hif-1α-glycolysis axis in lung macrophages during asthma, leading to lower levels of serum lactate." (PMID 41531823, 2026). "Second, during asthma exacerbations, airway obstruction leads to hypoxia, which in turn releases hypoxia-inducible factor (HIF-1α), resulting in endothelial dysfunction." (PMID 40703256, 2025). "Previous studies have shown that vitamin D improves asthma-induced lung damage by modulating the HIF-1α signaling pathway." (PMID 40165005, 2025). "In this study, we observed upregulation of HIF-1α in a mouse model of asthma, consistent with previous research." (PMID 39061007, 2024). "Through literature search, we found that the research on IL6, EGFR, and HIF1A to asthma was relatively richer compared with these of other targets." (PMID 38590639, 2024). "Evidence indicates that PI3K has essential roles in different aspects of asthma through HIF-1α-mediated VEGF expression." (PMID 37717070, 2023). "The tested compound alleviates asthma symptoms in mice by suppressing HIF-1α/VEGFA-mediated M2 macrophage skewing." (PMID 37174726, 2023). "While the induction of HIF-1 signaling is often considered in the context of tumorigenesis/carcinogenesis, aberrant HIF-1α signaling also occurs in asthma, COPD, lung inflammation, acute lung injury, and ischemic lung injury." (PMID 38464699, 2023). "Recent studies have uncovered the key role of the PI3K-Akt/HIF-1α pathway in airway remodelling in asthma." (PMID 37655452, 2023). "Earlier studies have also suggested that PI3K/Akt can modulate airway inflammation, AHR and vascular permeability through HIF-1α mediated regulation of VEGF in asthma pathogenesis." (PMID 37316684, 2023). "In BALB/c-OVA model of asthma, the HIF-1α antagonist YC-1 suppressed HIF-1α expression and lowered the transcript levels of IL-5, IL-13, myeloperoxidase, and NOS2." (PMID 35453294, 2022).
asthma (continued). "Vitamin D improved asthma‐induced lung tissue injury by suppressing autophagy via regulation of HIF‐1α/Notch1 (hypoxia‐inducible factor 1 alpha/neurogenic locus notch homolog protein 1) signaling in vivo." (PMID 35959262, 2022). "Given the HIF‐1α/Notch1 agonistic activity, Vit D treatment inhibited apoptosis cell numbers, which were increased following asthma‐induced upregulation of autophagy." (PMID 35959262, 2022). "In this present study, airway epithelial cells LDHA and HIF-1α expression in asthmatic mice, and lactate dehydrogenase and lactic acid in alveolar lavage fluid were found obviously downregulated in asthma mice with sTSLP treatment." (PMID 35351157, 2022). "In this study, four hub genes including HIF1A, OCRL, NNMT, and PER1 were identified as potential markers associated with asthma metabolism by bioinformatics analysis." (PMID 36676950, 2022). "Through machine learning and bioinformatics techniques, four hub genes, including HIF1A, NNMT, OCRL, and PER1, were identified as potential markers associated with asthma metabolism, especially HIF-1A." (PMID 36676950, 2022). "Vitamin D improved asthma‐induced lung tissue injury by suppressing autophagy via regulation of HIF‐1α/Notch1 signaling in vivo." (PMID 35959262, 2022). "Using RT-qPCR and Western blot analysis YAP and HIF-1α expression levels were found significantly higher in patients with asthma (p < 0.05)." (PMID 33980319, 2021). "In general, further studies with different cell lines, different disease models, and larger cohorts are essential to validate the findings of the current study and validate the translational potential of the YAP/HIF-1α/miR-182/EGR2 signaling axis in asthma." (PMID 33980319, 2021). "One of the important findings of the current study is that the factors YAP1 and HIF-1α were both increased in pediatric asthma." (PMID 33980319, 2021). "In conclusion, the findings in the current study demonstrated that YAP/HIF-1α enhanced Th17 cell differentiation, consequently exacerbating asthma and lipid metabolism dysfunction via miR-182-mediated EGR2 inhibition." (PMID 33980319, 2021). "During the induction phase of asthma, treatment with HIF-1α inhibitor is shown to decrease eosinophilia in bronchoalveolar lavage samples, lung parenchyma, and total lung inflammation." (PMID 33980319, 2021). "The aim of this study was to investigate if the Yes-associated protein (YAP)/hypoxia inducible factor-1α (HIF-1α)/microRNA-182 (miR-182)/early growth response 2 (EGR2) axis is involved in mediating Th17 cell differentiation and disease severity in asthma." (PMID 33980319, 2021). "Consistently, HIF-1α antagonist YC-1 reduced airway hyperresponsiveness and lung inflammation in a murine model of asthma." (PMID 33519814, 2020). "The aim of the present study is to understand how MBD2 interacts with HIF-1α to regulate Th17 cell differentiation and IL-17 expression in neutrophils-dominant asthma." (PMID 30150897, 2018). "Our findings have uncovered new roles for MBD2 and HIF-1α, and provide novel insights into the epigenetic regulation of neutrophils-dominant asthma." (PMID 30150897, 2018). "For example, HIF-1α expression is increased in asthma patients’ lung tissue and BALF and is also increased in patients experiencing rhinitis stimulated by antigens." (PMID 30150897, 2018). "Our study suggested that MBD2 regulates Th17 cell differentiation and IL-17 expression in neutrophils-dominant asthma through HIF-1α." (PMID 30150897, 2018). "Our previous work indicates that, compared to healthy volunteers, MBD2 and HIF-1α expression in CD4+ T cells was increased in the peripheral blood of patients with asthma." (PMID 30150897, 2018).
asthma (continued). "MBD2 and HIF-1α expression were significantly increased in the lung and spleen cells of mice with neutrophils-dominant asthma." (PMID 30150897, 2018). "Of note, HIF1α deletion in mice has been shown to ameliorate OVA-induced asthma with lower eosinophil infiltrations, reduced goblet cell hyperplasia and lower Th2 cytokine levels." (PMID 28383034, 2017). "As expected, the expression of HIF-1α was shown to be upregulated in the testis of mouse model of asthma." (PMID 26938720, 2016). "Previously, it has been demonstrated that HIF-1α expression is potentiated in the lung of asthma mouse models, as well as in BALF cells from asthmatic patients." (PMID 26938720, 2016). "Recently, postnatal loss (PN4-30) of Hif-1α from Clara and ATII cells was shown to bias the tissue towards a Th2 inflammation in a cobalt-induced toxicity model, similar to asthma." (PMID 26422241, 2015). "The HIF-1α subunit has been already proposed as a therapeutic target in asthma and effectiveness of HIF-1 inhibitors in reducing the symptoms of allergic rhinitis has been reported in mouse models." (PMID 26292153, 2015). "As well in studies on asthma, it has been found that overexpression of HIF-1α is involved in the development of allergic airway inflammation." (PMID 24312355, 2013). "We recently reported that HIF-1α is increased after allergic challenge in asthma and rhinitis patients." (PMID 22823210, 2012). "The association of HIF-1α and CCL2 levels was also measured in endobronchial biopsies and bronchial fluid of asthma patients after challenge." (PMID 22823210, 2012). "Recent research has also shown promise of therapeutic intervention of the HIF-1α as well PI3K/Akt signaling pathways for treatment of asthma and other related allergic conditions." (PMID 21625490, 2011). "Additionally, it has been shown in the literature that HIF-1α can interact with ubiquitin-related modifier proteins to promote the development of asthma." (PMID 39061007, 2024). "A notable increase in HIF-1α was observed in both in vivo and in vitro asthma models." (PMID 39061007, 2024). "At present, many studies have reported that HIF-1α is also a key inflammatory regulator of asthma." (PMID 36676950, 2022). "We identified a novel mechanism that lTSLP could promote inflammatory cytokines production by miR-223/VHL/HIF-1α pathway to upregulate aerobic glycolysis in airway epithelial cells in asthma." (PMID 35351157, 2022). "In addition, it has been found that PM2.5 promoted the differentiation of TH17 cells by upregulating the expression of HIF-1α and enhancing glycolysis; thus, aggravating asthma." (PMID 36676950, 2022). "Recent research results show that HIF-1α is the key regulator of asthma inflammation." (PMID 35620222, 2022). "Allergen exposure could cause upregulation of HIF-1α and vascular endothelial growth factor (VEGF) in patients with asthma and rhinitis." (PMID 34421593, 2021). "Other studies have illustrated that deficiency of HIF-1α can reduce eosinophil infiltration, goblet cell hyperplasia, and levels of cytokines IL-4, IL-5, and IL-13 in the lungs of OVA-induced asthma models, further highlighting the importance of the elevated levels of HIF-1α in asthma." (PMID 33980319, 2021). "In addition, in vivo overexpression of EGR2 countered the promoting effect of the YAP/HIF-1α/miR-182 axis on asthma and lipid metabolism dysfunction." (PMID 33980319, 2021). "Besides its global impact on allergic airway inflammation, the functional role of HIF-1α in different subsets of immune cells has also been investigated in asthma." (PMID 33519814, 2020). "Hypoxia inducible factor-1α (HIF-1α) is involved in allergic responses in asthma." (PMID 30150897, 2018). "HIF-1α may be involved in the persistence and deterioration of neutrophils-dominant asthma through Th17 cell function and neutrophil recruitment." (PMID 30150897, 2018). "Understanding the role of MBD2 and HIF-1α in neutrophils-dominant asthma may offer a theoretical basis for treatment." (PMID 30150897, 2018).
asthma (continued). "Finally, we should mention that the nine-branched HIF-1α/Hypoxia pathways were up-regulated in BSM cells of asthma patients." (PMID 26863634, 2016). "Therefore, the inhibition of PKC δ by rottlerin is supposed to attenuate AHR and airway inflammation through suppressing the PI3K/Akt/mTOR/HIF-1α/VEGF pathway in an asthma model." (PMID 24312355, 2013). "Moreover, HIF-1α levels are increased in lung tissue and bronchial fluid of patients with asthma and in the nasal fluid of patients with rhinitis after allergen challenge." (PMID 23935964, 2013). "In asthma patients, the levels of HIF-1α and CCL2 increased after challenge with the allergen." (PMID 22823210, 2012). "However, the role of HIF-1α in airway inflammation induced by asthma and in the induction of airway remodeling remains unclear." (PMID 39061007, 2024). "Thus, we hypothesized that Lok protects against asthma via modulation of the PI3K-Akt/HIF-1α pathway." (PMID 37655452, 2023). "In the present study, we merged the differentially expressed genes (DEGs) of asthma in the GEO database with the metabolic genes obtained by Genecard for bioinformatics analysis and successfully screened out the metabolism-related hub genes (HIF1A, OCRL, NNMT, and PER1)." (PMID 36676950, 2022). "Thus, the YAP/HIF-1α/miR-182/EGR2 signaling may serve as a novel biomarker for asthma diagnosis and prognosis." (PMID 33980319, 2021). "Moreover, HIF-1α has been reported to facilitate the differentiation of Th17 cells, and may serve as an important signaling molecule for the induction of asthma by promoting Th17 cells." (PMID 33980319, 2021). "Therefore, it is logical to hypothesize that HIF-1α may be involved in the pathogenesis of neutrophils-dominant asthma by regulating differentiation of Th17 cells." (PMID 30150897, 2018). "Therefore, MBD2 may have a close relationship with the immunological pathogenesis of asthma and contribute to Th17 cell differentiation and IL-17 expression through HIF-1α." (PMID 30150897, 2018). "Thus, HIF-1α plays pivotal roles in angiogenesis, vasodilation, and vascular permeability, which may contribute to airway remodeling and inflammation in asthma." (PMID 24312355, 2013). "Furthermore, although CCL2 may not be considered an ideal pharmacotherapeutic target for the treatment of asthma, our results indicate that HIF-1α may be used as a specific target." (PMID 22823210, 2012). "Inhibiting hypoxia-inducible factor 1-alpha (HIF-1α) or disrupting glycolytic metabolism has been demonstrated to suppress ILC2 activity and mitigate airway inflammation in mouse models of asthma." (PMID 40355861, 2025). "Increased levels of p-PI3K, p-Akt, and HIF-1α were observed in the lungs of the asthma models, substantiating that the PI3K-Akt/HIF-1α pathway is tightly correlated with the development of asthma." (PMID 37655452, 2023). "But sTSLP decreased LDHA (lactate dehydrogenase A) and LD (Lactic acid) levels in BALF, and HIF-1α and LDHA protein levels in airway epithelial cells of asthma mice model." (PMID 35351157, 2022). "In the pathogenesis of asthma, with the activation of IL6 and Stat3 proteins, HIF-1α protein expression increases under the IL-6/Stat3/HIF-1α signaling pathway, which then promotes the apoptosis of spermatogenic cells, affecting sperm quality." (PMID 35620222, 2022). "YAP, HIF-1α, and miR-182 were upregulated but EGR2 was downregulated in human and mouse peripheral blood mononuclear cells from the asthma group." (PMID 33980319, 2021). "Asthma mice presented with elevated YAP and HIF-1α expression, but reduced EGR2 expression (p < 0.05)." (PMID 33980319, 2021). "Collectively, these results suggested that miR-182, YAP and HIF-1α were upregulated, and serum HDL-C level was decreased in asthma." (PMID 33980319, 2021).
asthma (continued). "Abundant expression of YAP and HIF-1α promoted miR-182 expression and then inhibited EGR2, a target of miR-182, thus enhancing Th17 differentiation and deteriorating asthma and lipid metabolism dysfunction." (PMID 33980319, 2021). "Meanwhile, vascular edema and increased expression of HIF-1α and HIF-2α were found in the brain of asthma model mice." (PMID 34248632, 2021). "In a murine asthma model, inhaled administration of budesonide significantly reduced the vascularity and the expression levels of HIF-1α and VEGF, supporting an anti-angiogenic role for budesonide in the treatment of human asthma." (PMID 33628848, 2021). "In a mouse model of asthma, suppression of HIF‐1α with YC‐1 reduced expression of IL‐5, IL‐13, myeloperoxidase (MPO) and inducible nitric oxide synthase (iNOS), which alleviated asthma symptoms." (PMID 32633061, 2020). "Pathway cross-talk analysis highlights that signaling pathways mediated by IL-4/13 and transcription factor HIF-1α and FOXA1 play crucial roles in the pathogenesis of asthma." (PMID 31430856, 2019). "A neutrophils-dominant asthma mouse model was established using female C57BL/6 mice to investigate Th17 cell differentiation and MBD2 and HIF-1α expression regulation using flow cytometry, western blot or qRT-PCR." (PMID 30150897, 2018). "Our findings uncover new roles for HIF-1α and MBD2, and provide novel insights into the epigenetic regulation of neutrophils-dominant asthma." (PMID 30150897, 2018). "Consistent with the RT-qPCR results, protein level of the anti-apoptosis gene Bcl-2 was significantly impaired in the testis of asthma mice, while the expression of AIF and HIF-1α was significantly induced in the asthmatic testis." (PMID 26938720, 2016). "In summary, we have shown herein that treatment of allergic mice with rottlerin results in the inhibition of PKC δ and the subsequent disruption of a PI3K/Akt/mTOR/HIF-1α/VEGF module, thereby reversing all pathophysiologic symptoms of asthma." (PMID 24312355, 2013). "Administration of insulin-like growth factor (IGF) binding protein, specifically IGFBP-3, reduced HIF-1α/HIF-2α signaling, which mediates VEGF expression, and IGF-I production, contributing to reduced VEGF expression, airway inflammation, and bronchial hyperreactivity." (PMID 37174726, 2023). "Our findings suggest that Lok significantly prevents EMT progression by reducing TGF-β1 production in epithelial cells, alleviating airway inflammation and remodelling in experimental asthma models by suppressing EMT via downregulating PI3K-Akt and HIF-1α expression." (PMID 37655452, 2023). "MBD2 increases HIF-1α in neutrophil-dominant asthma and is involved in increased differentiation and secretion of Th17 cells and IL17 through regulating the HIF-1α expression and also reduces the Treg function through an increase in HIF-1α suggesting the epigenetic role of MBD2 in severe asthma." (PMID 35096261, 2021). "Based on these results we validated the hypothesis that amplified EGR2 eliminated Th17 cell differentiation, asthma, and lipid metabolism dysfunction driven by YAP/HIF-1α/miR-182 signaling." (PMID 33980319, 2021). "In addition, asthma mice treated with oe-YAP, oe-HIF-1α, or miR-182 mimic presented with reduced HDL-C levels, while increased HDL-C levels were found in response to EGR2 overexpression (p < 0.05)." (PMID 33980319, 2021).